WNT5A (Wnt family member 5A)
Diseases named in the same sentence as WNT5A in open-access papers (continued):
Sharing a sentence is not in itself a finding about the gene and the disease.
infection (continued). "Enhanced IL36γ secretion during infection induces Wnt5A expression which aids in controlling infection through COX-2 mediated autophagy." (PMID 31736969, 2019). "To further analyze NSC activation status after injury we quantified ki67+ cell numbers in the SVZ at 7DPI after LacZ or Wnt5a-AAV infection." (PMID 29296000, 2018). "Overall, our study unveils the prevalence of a Wnt5A—Rac1—Disheveled-mediated actin-associated autophagy circuit as an important component of innate immunity in host macrophages that may turn out crucial for restricting infection by leading bacterial pathogens." (PMID 29686674, 2018). "Our results indicate that Wnt5A levels and pathogenic bacterial load are inversely correlated and that macrophage Wnt5A signaling can potentially be suppressed by bacterial pathogens associated with COPD and other important human infections." (PMID 29686674, 2018). "In view of the fact that macrophage interactions with bacteria can potentially vary with differences in species and their pathogenicity, we investigated the interrelation between Wnt5A signaling and infection by leading bacterial pathogens, such as PA and SP." (PMID 29686674, 2018). "We found that during the initial hours of infection with PA and SP, there is decrease in the steady state levels of the Wnt5A protein in macrophages." (PMID 29686674, 2018). "Infection of a second macrophage line (J774.1A) pretreated with Wnt5A vs. PBS produced similar results." (PMID 29686674, 2018). "With regard to infections, Wnt5a induction has been described in response to a variety of pathogens." (PMID 28082976, 2016). "Inhibition of the demethylation at H3K27 by GSK J4 led to the opposite expression pattern with a significant increase in the WNT5A in the infection group." (PMID 26964089, 2016). "WNT5A has been reported by others as a regulator of epithelial and uroepithelial cell growth during regeneration as well as post-infection." (PMID 26964089, 2016). "The simultaneous increase in inflammatory cytokines produced by the infiltrating immune cells that attack the site of infection can increase Wnt5a levels even further." (PMID 24981738, 2014). "Semi-quantitative PCR revealed significant increases in both Wnt2b and Wnt5a expression in YAMC cells at 48 h post-CR infection compared to uninfected control." (PMID 24278135, 2013). "Infection of hDPCs with both RhoA T19N and RhoA Q63L adenovirus for 48 hr blocked the effect of Wnt5a CM on adhesion and migration, while RhoA Q63L showed a similar inhibition of cell migration with or without Wnt5a." (PMID 23844260, 2013). "Wnt5a knockdown on the other hand, resulted in an increase in reporter activity which was further enhanced following CR infection." (PMID 24278135, 2013). "For instance, infection of chick limbs using a retrovirus carrying Wnt5a or Wnt4 presented distinct effects, with Wnt5a delaying chondrocyte differentiation, whereas Wnt4 accelerated it." (PMID 17505543, 2007). "The importance of this study lies in the fact that it unveils a potential role of a growth factor termed Wnt5A in the safeguarding of the gut B-cell population and microbiota, thereby protecting the gut from the deleterious effect of infections by common pathogens." (PMID 39140737, 2024). "The potential role of the Wnt5A–gut microbiota axis in the maintenance of gut B-cell repertoire and protection from the harmful effects of infection, as projected through this study, opens up new avenues for further investigations into the role of Wnt5A signaling in gut health and disease." (PMID 39140737, 2024). "Aberrant Wnt5a expression has been observed in infection, inflammation, and immunity." (PMID 38062395, 2023). "Other biologically relevant Wnt5a-dependent processes, for example, cell-specific responses to infection or SCRIB-dependent processes – including ones directing apical-basal polarity – may be impacted by the OTULIN-SCRIB interaction and Met1-Ub homeostasis." (PMID 37589075, 2023).
infection (continued). "Progression of infection in mice by both antimony sensitive and antimony resistant strains of L. donovani could be prevented by activation of Wnt5A signaling through intravenous administration of rWnt5A prior to L. donovani infection." (PMID 35197983, 2022). "However, infection prevailed in the spleen, especially in most of the Wnt5A heterozygous mice even after 110 days." (PMID 35197983, 2022). "Additionally, we showed that the degree of activation of Wnt-5a is affected by TSP1 expression during the early phase of infection." (PMID 34986160, 2022). "Accordingly, Wnt5A signaling may be envisaged as a regulator of immune resistance to harmful infections." (PMID 33664738, 2020). "In view of the role of Wnt5A signaling in actin assembly, we studied how the Wnt5A–Actin axis regulates the outcome of infection by a bacterial pathogen (E. coli K1 isolate from a biliary sepsis patient) as compared to a non-pathogen (lab strain E. coli DH5α or E. coli K12-MG1655)." (PMID 33664738, 2020). "Moreover, neutrophils are among the first lines of defense because they are recruited to an area of infection or injury, and Wnt5a mediates this process." (PMID 31684152, 2019). "Wnt5a induces a proinflammatory response not only during infection and organ repair or injury; for example, a study suggests that Wnt5a may activate an immunosuppressive response in macrophages in both humans and mice." (PMID 31684152, 2019). "In vitro studies showed that infection of monocytes and macrophages of human and mouse origin with mycobacteria across a virulence spectrum (M. tuberculosis, M. avium, M. bovis Bacillus Calmette-Guérin) greatly enhanced expression of WNT5A." (PMID 31781093, 2019). "A small molecule IWP2 was used to block Wnt5A signaling prior to infection, under each condition." (PMID 29686674, 2018). "We have found that Wnt5A signaling in the host restricts spread of infection by leading human bacterial pathogens PA and SP, despite their potential to suppress Wnt5a protein levels and macrophages constitute an important component of this innate immune defense program." (PMID 29686674, 2018). "Whether or how Wnt5A signaling affects progression of infection by such pathogens is an important matter to investigate." (PMID 29686674, 2018). "Activation of Wnt5A signaling, on the other hand, enhances clearance of the infection." (PMID 29686674, 2018). "To determine how intracellular bacterial infection per se affects Wnt5A signaling in macrophages we compared levels of cell-associated and secreted Wnt5A in PA- and SP-infected vs. uninfected macrophages using different multiplicities of infection (MOI: bacteria/cell) and durations of infection." (PMID 29686674, 2018). "In addition to human and murine cells, an increased expression of Wnt5a was also observed in Mycobacterium marinum-infected adult zebrafish, demonstrating that induction of Wnt5a upon infection is a conserved mechanism." (PMID 28082976, 2016). "Thus, WNT-5A is suggested to contribute to the immune system readiness for countering any future infection." (PMID 26514730, 2016). "However, it has also been shown that UPEC induces infected cells to secrete paracrine factors that cause alterations in the expression of the epigenetic writer EZH2 which enhances Wnt5a expression, promoting proliferation of infected cells at relatively early infection time points." (PMID 31681283, 2019). "Interestingly, blockade in Wnt5A signaling also inhibits infection by the non-pathogenic lab strain of E. coli, DH5-α, which gets internalized but not killed by activation of Wnt5A signaling." (PMID 31736969, 2019). "However, our observed increase in WNT5A mRNA during infection was reversed with the inhibitor of EZH2 suggesting that a transcriptional repressor may be regulated by EZH2 in this case." (PMID 26964089, 2016).
infection (continued). "We further confirmed that WNT5A, SELENON, and SLC16A13 are key host factors involved in infection by BPIV-3a, as well as by BPIV-3c and other bovine RNA viruses (e.g. BEV)." (PMID 41328592, 2025). "Conversely, we ectopically expressed WNT5A in WNT5A-mutant cells, which restored BPIV-3a titers to WT levels at 24 h post-infection (hpi, MOI 0.1)." (PMID 41328592, 2025). "In case of K1 infection, the optimal condition was obtained through activation of Wnt5A signaling, but in case of K12-MG1655 or DH5α infection, additional influence of actin assembly inhibitor was required." (PMID 33664738, 2020). "Decreased Wnt5a protein and decreased Ctnnb1 mRNA expression in the mouse macrophage cell line RAW264.7 have also been reported upon infection with Pseudomonas (P.)aeruginosa." (PMID 31781093, 2019). "No notable effect of the inhibitors on the infection load in PBS (control for Wnt5A) treated macrophages suggested that the inhibitors were active only when actin assembly was stimulated by Wnt5A signaling." (PMID 33664738, 2020). "With Wnt5a expression reported to be suppressed by S. pneumoniae and P. aeruginosa infection of macrophages, roles of other WNT ligands responsive to infection (e.g., Wnt4, Wnt5b, Wnt7a, Wnt7b) and the net-outcome of WNT signaling in infected cells will need further exploration." (PMID 31781093, 2019). "Wnt5A signaling can also influence transcriptional regulation of immune response genes such as TNFα, IFNγ, and IL6, which have interrelation with actin dynamics and are known to work toward inhibition of pathogen infection." (PMID 31736969, 2019). "Infection by FimH+ UPEC results in a decrease in Wnt5a expression and subsequent decrease of non-canonical Wnt pathway targets PKCδ and CamKIIδ up to relatively late infection timepoints." (PMID 31681283, 2019). "Here, we describe how Wnt5A, a representative non-canonical Wnt programs macrophages for host defense against infections by leading bacterial pathogens utilizing host cytoskeleton and the associated Rac1—Disheveled coupled autophagy circuit." (PMID 29686674, 2018). "The infected mice exhibited increased mRNA levels of canonical (Wnt1, Wnt2, Wnt3, and Wnt3a) and noncanonical (Wnt5a) Wnt molecules, receptors (Fz1 and Fz5) and the Wnt signalling target gene Sox9 in hepatocytes at 6 and 12 weeks post-infection." (PMID 28331224, 2017). "Basal WNT-5A expression by macrophages drives static IFN-β and -γ expression via a Rac1-NFκB pathway and also regulates expression of CD14 which is required for antigen recognition and innate immune responses during infection." (PMID 26514730, 2016). "During the course of infection, alveolar epithelial cells start to produce Wnt5a that adds to the already increased Wnt5a levels produced by the aging nonepithelial elements of the distal lung." (PMID 24981738, 2014). "After infection with RhoA T19N or RhoA Q63L adenovirus for 48 hr, Wnt5a CM did not up-regulate the expression of phospho-MLC, which is consistent with the effect on cytoskeleton rearrangement." (PMID 23844260, 2013). "So far it is not known if levels of WNT-5A or its receptors are dynamically regulated under pathophysiological conditions, such as neurodegenerative disease, infection, trauma, hypoxia or other inflammatory conditions." (PMID 22647544, 2012). "The extent of sIgA-bound bacteria in both wild-type and Wnt5A heterozygous mice was the same despite the presence of increased IgA-expressing B cells in the heterozygous, suggesting lack of sIgA-mediated suppression of infection through bacterial binding." (PMID 39140737, 2024). "Upon infection by mycobacteria, WNT5A was induced in antigen-presenting T cells in a TLR-NF-κB-dependent manner, where it mediates the secretion of IL-12 and IFN, and both WNT5A and WNT3A were found to inhibit TLR-induced secretion of proinflammatory cytokines in DC." (PMID 35742983, 2022).
infection (continued). "In compliance with the results obtained with Wnt5A heterozygous and wild type mice, we found that prior injection of rWnt5A but not rWnt3A or just the vehicle control (PBS) in BALB/c mice inhibits both the degree of infection with L. donovani and the progression of disease." (PMID 35197983, 2022). "Overexpression of CYP1A1 by Wnt5A may enhance erythromycin’s metabolism and thus affects its half-life leading to the persistence of infection and lack of drug efficiency." (PMID 34079452, 2021). "Activation of Wnt5A signaling through added rWnt5A (using PBS as vehicle control), on the other hand, led to significant increase in assembled actin (F-actin) in K1 infected but not K12-MG1655 or DH5α infected RAW264.7 cells during 3 h post infection (T3), as demonstrated by immunoblotting." (PMID 33664738, 2020). "SP- and PA-infected RAW 264.7 macrophages (1 h infection) treated with IWP2 for 24 h, accumulated considerably less (40–60%) LC3BII as compared to the corresponding controls, in agreement with suppressed bacterial clearance in Wnt5A depleted condition as depicted before." (PMID 29686674, 2018). "This dependency of WNT5A expression on EZH2 during infection has not been previously noted." (PMID 26964089, 2016). "Thus, while significant increase in actin assembly by Wnt5A as compared to control (PBS) in the case of E. coli K1 infection correlated with appreciable bacterial killing, no significant change in actin assembly by Wnt5A in the case of K12-MG1655 or DH5α infection correlated with survival." (PMID 33664738, 2020). "Thus, Wnt5a and not Wnt2b regulates NF-κB activity in response to CR infection." (PMID 24278135, 2013).
cardiovascular diseases (13 papers, 2016 to 2025). "The present study suggests that Wnt5a might be a possible common mechanism linking both RA and cardiovascular disease." (PMID 28724439, 2017). "Multivariate analysis identified elevated Wnt5a, JAK, and decreased SFRP5 as independent predictors of cardiovascular disease (p < 0.05)." (PMID 41465371, 2025). "Here, we find that in HCAEC, Wnt5A critically modulates myocardium-specific pharmacokinetic pathways by upregulating the transcription of CYP enzymes that are known to metabolize a broad spectrum of drugs including those used in immune system and cardiovascular diseases." (PMID 34079452, 2021). "Previous studies unanimously reported that SFRP5 exerted an anti-inflammatory effect by inhibiting the non-canonical Wnt5a/JNK signaling pathway, therefore playing a key role in repressing the occurrence and development of various diseases including obesity, cardiovascular diseases, and diabetes." (PMID 35506262, 2022).
bacterial infection (7 papers, 2016 to 2022). "As in the case of bacterial infection, Wnt5A mediated inhibition of L. donovani infection is blocked by inhibitor of Rac1 activation, which is linked with Wnt5A mediated cytoskeletal alterations." (PMID 31736969, 2019). "Accordingly, we focused on macrophages to decipher the interrelation between Wnt5A signaling and pathogenic bacterial infection." (PMID 29686674, 2018). "Keeping in mind the documented role of Wnt5A signaling in the regulation of bacterial infections and immune homeostasis, we became interested in evaluating the influence of Wnt5A on L. donovani infection and progression of VL." (PMID 35197983, 2022). "Accordingly, we first studied the effect of the bacterial infections on actin assembly and then examined if activation of Wnt5A signaling in the infected cells introduces alterations in the scenario." (PMID 33664738, 2020). "Quite naturally, Wnt5A signaling is an important facet of macrophages, which respond to a broad spectrum of environmental cues including bacterial infections, through alterations in cell migration and polarity." (PMID 33664738, 2020). "Wnt5A signaling was activated both in RAW 264.7 and mouse peritoneal macrophages by recombinant Wnt5A (rWnt5A) treatment (50 ng/ml) for 6 h prior to bacterial infection." (PMID 33664738, 2020). "Overall, our data indicate that Wnt5A signaling controls the outcome of different bacterial infections at least partly through actin organization." (PMID 33664738, 2020). "Our documentation of regulation of bacterial infections by a Wnt5A—Rac1—Disheveled mediated autophagy circuit unveils an as yet uncharacterized component of host pathogen interactions in the innate immune defense program." (PMID 29686674, 2018). "Suppression of Wnt5A signaling, moreover, impairs macrophage clearance of the bacterial infection both in vitro and in vivo." (PMID 29686674, 2018). "Macrophage-mediated containment of bacterial infection in our study is dependant on Wnt5A-induced Rac1/Disheveled activation and cytochalasin D inhibitable actin assembly, which is associated with ULK1 kinase activity and LC3BII accumulation." (PMID 29686674, 2018). "The intrinsic association of cytoskeletal actin with bacterial infections led us to investigate if killing vs. survival of the pathogenic and non-pathogenic E. coli by Wnt5A signaling is associated with actin assembly." (PMID 33664738, 2020). "Both Wnt5A signaling and bacterial infection act together to stimulate LC3BII accumulation, a well known marker of autophagy and LC3B reactive puncta correlate significantly with Wnt5A facilitated bacterial clearance as depicted by bacterial killing assays, western blotting, and confocal microscopy." (PMID 29686674, 2018). "We note that Wnt5A signaling, which defends against bacterial infection influences actin assembly." (PMID 29686674, 2018). "Thus, it may be stated that bacterial infections in macrophages can be managed through changes in the degree of actin assembly by regulation of Wnt5A signaling through activation by rWnt5A and application of specific inhibitors at appropriate dosages." (PMID 33664738, 2020). "Notably, unlike macrophages, the exact role of macrophage-derived Wnt5a in bacterial infection remains largely unknown." (PMID 27608847, 2016).
inflammation (7 papers, 2014 to 2026). Aberrant reaction of the microcirculation characterized by movement of fluid and leukocytes from the blood into extravascular tissues. "Wnt5a induces endothelial inflammation and contributes to CXC chemokine 12-ligand mediated T-cell migration." (PMID 28082976, 2016). "Lungs from septic animals and from septic humans demonstrated acute lung inflammation, collagen deposition, and marked increase of WNT5A and MMP7 protein levels." (PMID 25331176, 2014). "Previously, the Wnt5a–ERK pathway was proposed as a mechanism whereby PM2.5 could aggravate smoking-induced airway inflammation." (PMID 38654364, 2024). "Wnt5A is a non-canonical Wnt ligand, recently identified as a pro-inflammatory mediator of macrophage activation in vascular inflammation." (PMID 27214384, 2016).
adenocarcinoma (6 papers, 2014 to 2026). A common cancer characterized by the presence of malignant glandular cells. "In the CAC model mice, we observed Wnt3a, Wnt5a, β‐catenin, and non‐phosphorylated (activated) β‐catenin were markedly upregulated in early adenocarcinoma tissues." (PMID 39302044, 2024). "Inferred plasma transcriptomes distinguished adenocarcinoma vs. neuroendocrine phenotypes and identified a noncanonical WNT5A-associated signature linked to poor clinical response." (PMID 41674842, 2026). "The study found significant molecular changes in adenocarcinoma tissues from a CAC mouse model, including increased expression of Wnt3a and Wnt5a proteins, total β‐catenin protein, and activated β‐catenin." (PMID 39302044, 2024).
kidney disease (6 papers, 2016 to 2022). "However, our study also provided interesting evidence that wnt5a gradually increased in long-term T2DM patients with kidney disease." (PMID 31890678, 2019). "Thus reduction of the P4ha1 mediated compensation in the absence of Wnt5a function aggravates the renal disease phenotype." (PMID 26794322, 2016).